NOG (noggin)
Diseases named in the same sentence as NOG in open-access papers (continued):
Sharing a sentence is not in itself a finding about the gene and the disease.
cancer (28 papers, 2011 to 2025). A tumor composed of atypical neoplastic, often pleomorphic cells that invade other tissues. "Noggin is low in normal and cancer tissues, and mutations and amplifications are rare." (PMID 40212011, 2025). "To test whether BMP signaling affects the self-renewal potential of cancer cells, we treated Pten-deficient basal prostate organoids with the inhibitory protein NOGGIN." (PMID 32894216, 2020). "Noggin has been shown to have anti-cancer effects by inhibiting the activity of BMPs, which are a group of proteins that belong to the TGF-β superfamily and are involved in various cellular processes such as cell proliferation, differentiation, and migration." (PMID 38012621, 2023). "A challenge is to demonstrate that Noggin can prevent cancer under the complex patho-physiological conditions as exist in DGERD as seen in Barrett’s patients." (PMID 34718471, 2022). "Growth factors for cancer organoid culture include Wnt3A, R-spondin-1, TGF-β receptor inhibitor, epidermal growth factor, and Noggin, but the combination and concentration of these factors added to the media depend on the specific cancer type." (PMID 36713421, 2022). "Given that only some cancers express high levels of gremlin and noggin we sought to investigate their inhibitory effects on both BMP4 and BMP7v." (PMID 31591478, 2020). "PRDC, a GREM1 homologue showing strong resemblance to Noggin and Chordin as well, was recently connected to cancer progression." (PMID 32486027, 2020). "It is noteworthy that although many BMP antagonists have been identified, only a few are being researched in the context of cancer: Noggin, Gremlin and, to a lesser extent, Chordin, Sclerostin and PRDC." (PMID 32486027, 2020). "The link between Noggin and cancer has been mainly investigated in cancers metastasizing to the bone." (PMID 32486027, 2020). "We show that BMP pathway activation is associated with an increase in the migratory capacity of carcinoma cells, an effect that can be ablated by the BMP antagonist, Noggin." (PMID 32708289, 2020). "The results also suggest that increased BMP signalling within EBNA1-expressing carcinoma cell lines, as well as in EBV-infected Ad/AH cells, contributed to this increase in cell migration, as it was susceptible to reduction by Noggin." (PMID 32708289, 2020). "Conversely, suppression of cancer cell-derived noggin restores the bone formation phase, which is physiologically coupled to the initial phase of bone resorption." (PMID 21249149, 2011). "Conversely, cancer cell-secreted noggin prevents the repair of osteolytic lesions by uncoupling bone formation from the osteoclast-mediated bone resorption, which is stimulated by cancer cell-derived osteolytic cytokines." (PMID 21249149, 2011). "In contrast, noggin silencing in PC-3 cells targets exclusively the noggin of cancer cell origin, thereby eliminating its interference with the physiological BMP/noggin balance within the bone microenvironment." (PMID 21249149, 2011). "Among the possible candidates, we further analyzed DNMT1, CCKBR, WNT10B, NOG and ROBO1, which are five genes whose functions have been associated with carcinogenesis or cancer development." (PMID 21205300, 2011). "We think that these oncogenic features may confer a growth advantage to KRAS-mutant cancer cells under 3D culture conditions, especially in our system, where additional growth factors such as Wnt3a, R-spondin-1, and Noggin were excluded." (PMID 40462147, 2025). "Recent findings have established a key role for Noggin and perturbation of BMP signalling as a mechanism contributing to denervation and cancer‐induced muscle loss, thereby supporting this axis as a potential contributor to diaphragm wasting in response to PDAC." (PMID 39810606, 2025). "Notably, we avoided using organoid culture media components such as Wnt3a, R-Spondin-1, and Noggin, which are known to influence the molecular subtypes of cancer cells." (PMID 40462147, 2025).
cancer (continued). "We overexpressed Noggin in M2 cells and checked its effects on cancer cell migration." (PMID 38012621, 2023). "Pro- and anti-cancer effects of Noggin are complex and dependent on the specific cancer type and context; therefore, further research is needed to fully understand the role of Noggin in cancer development and to explore its potential as a therapeutic target for cancer treatment." (PMID 38012621, 2023). "Treatment was initiated at 26 weeks after surgery to investigate if the BMP inhibitor Noggin could attenuate cancer development." (PMID 34718471, 2022). "The NOGGIN gene resides on chromosome 17q22, and is generally deleted in human cancers." (PMID 34001012, 2021). "In addition, several in vitro studies have found Noggin to be downregulated in cancer cell lines of different origin and it has the ability to counteract the tumorigenic processes initiated by BMPs, for example, proliferation, migration, etcetera." (PMID 32486027, 2020). "A number of aging- and cancer-associated genes were observed among the 420 predicted bowhead-minke orthologs with dN/dS exceeding 1, including suppressor of cytokine signaling 2 (SOCS2), aprataxin (APTX), noggin (NOG), and leptin (LEP)." (PMID 25565328, 2015). "We then argued that, in analogy to what has been found for Dkk-1 in MM, constitutive noggin release by osteolytic cancer cells might contribute, through inhibition of bone formation, to the osteolytic lesion in bone metastases of solid cancers." (PMID 21249149, 2011). "This investigation provides new evidence for a model of osteolytic bone metastasis where constitutive secretion of noggin by cancer cells mediates inhibition of bone formation, thereby preventing repair of osteolytic lesions generated by an excess of osteoclast-mediated bone resorption." (PMID 21249149, 2011). "Therefore, in order to extend the relevance of noggin in cancer-mediated osteolysis, it will be important to confirm the present findings in a CaM model of osteolytic bone metastasis." (PMID 21249149, 2011). "Bone metastatic cancer cells may interfere with this balance by secreting an excess of either BMPs or noggin." (PMID 21249149, 2011). "However, in one of these reports we demonstrated that, in addition, osteoinductive cancer cells lack secretion of the BMP inhibitor noggin and that noggin forced expression in these cells abolishes their osteoinductive activity in vivo." (PMID 21249149, 2011). "Osteoinductive cancer cell lines lack noggin expression, and the functional relevance of this finding was emphasized by showing that noggin forced expression in an osteoinductive CaP cell line abolishes the osteoblast response induced by its bone metastases in vivo." (PMID 21249149, 2011). "As a result, the physiological BMP/noggin balance in bone could be tilted in favor of first by an excess of cancer cell-derived BMPs, which may explain the trend toward increase in bone formation observed in bone xenografted with Nog-KD PC-3 cells." (PMID 21249149, 2011). "We hypothesized that cancer cell-derived noggin may contribute to the pathogenesis of osteolytic bone metastasis of solid cancers by repressing bone formation." (PMID 21249149, 2011). "In contrast, osteolytic, carcinoma-derived cell lines express noggin constitutively." (PMID 21249149, 2011). "However, Noggin can also have pro-cancer effects in certain contexts." (PMID 38012621, 2023). "The positive effect of noggin silencing on bone formation supports our original hypothesis and suggests noggin as one of the essential cancer cell-derived inhibitors of the osteoblast recruitment/activity contributing to the osteolytic lesions in CaP bone metastases." (PMID 21249149, 2011). "Furthermore, the demonstration that specific targeting of the cancer cell-derived noggin preserves bone formation/repair strongly suggests noggin as a major “un-coupling factor” in osteolytic bone metastasis and further emphasizes the relevance of BMP antagonism in pathological bone remodeling." (PMID 21249149, 2011).
cancer (continued). "For instance, to generate mixed microtissues between hepatocyte-like and cancer cells, the HepatiCult ODM was supplemented with Noggin, which is indispensable for cancer organoid growth." (PMID 39836518, 2025). "Noggin is a secreted protein that belongs to the BMP antagonist family, and it has been found to play a complex and context-dependent role in cancer development." (PMID 38012621, 2023). "Noggin, similar to DKK1, acts as an antagonist to osteoinductive Wnt proteins in osteolytic cancer cells, and as expected, noggin is not expressed in osteoinductive cancer cell lines." (PMID 34685470, 2021). "BMP7v is the only reported systemically available BMP in the context of cancer therapy and, when combined with a marked reduction in binding to endogenous BMP inhibitors such as chordin, chordin-like 2 and noggin represents a potentially significant advance in the field." (PMID 25919028, 2015). "Bone formation was preserved in the osteolytic lesions induced by noggin-silenced PC-3 cells, suggesting that cancer cell-derived noggin interferes with physiologic bone coupling." (PMID 21249149, 2011). "This suggests that interference with the constitutive secretion of noggin by cancer cells does not affect the early steps of the bone metastatic colonization (adhesion and extra-vasation) and, especially, the growth initiation by the osteolytic process." (PMID 21249149, 2011). "Lack of expression of the BMP antagonist noggin by osteoinductive, carcinoma-derived cell lines is a determinant of the osteoblast response induced by their bone metastases." (PMID 21249149, 2011). "In addition, we found that the BMP targets, ID1 and ID2, were significantly downregulated in the carcinomas, whereas GREM1 and NOG expression increased, albeit not significantly in the case of GREM1." (PMID 27492255, 2016).
infection (2 papers, 2014 to 2024). The state of being infected such as from the introduction of a foreign agent such as serum, vaccine, antigenic substance or organism. "Implantation of Noggin-soaked beads in the FnP mesenchyme at HH15/16 or infection of neural crest cells at HH10 with a replication-competent retrovirus encoding the Bmp antagonist Noggin (RCAS-Noggin) abolished Shh expression in the ventral domains of FEZ." (PMID 39583201, 2024).
kidney diseases (2 papers, 2009 to 2025). "Of note, the expression of agents described as endogenous antagonists of BMPs such as noggin and USAG-1 strongly increased with the progression of renal disease in RenTg, and decreased to normal levels during AT1 receptor treatment." (PMID 19696925, 2009).
adenocarcinoma (1 paper, 2015). A common cancer characterized by the presence of malignant glandular cells. "To pursue this, we micro-dissected and dissociated adenocarcinomas from Lin28bLo/Let7IEC-KO mice and cultured “tumoroids” from these lesions in medium supplemented with EGF, Noggin, and Rspo1 for enteroid culture." (PMID 26244988, 2015).
bone disorder (1 paper, 2023). "Multiple bone disorders due to mutations in the human noggin (NOG) causes a variety of phenotypes." (PMID 37045840, 2023).
genetic diseases (1 paper, 2019). "Mutations in these two regions impair the antagonizing function of noggin, causing the dysregulated activation of the type I and type II receptors, that results to a variety of genetic diseases in bone development." (PMID 31105738, 2019).
neurodegenerative disease (1 paper, 2016). A disorder of the central nervous system characterized by gradual and progressive loss of neural tissue and neurologic function. "Our data also suggest a progressive imbalance of the Bmp6/Noggin ratio that may negatively affect proliferation, differentiation and activity of many cell types, and may be related to the pathophysiology of neurodegenerative diseases." (PMID 27545843, 2016).
skeletal dysplasia (1 paper, 2019). Any Mendelian diseases that affects growth and development of the skeleton. "In humans, NOG missense mutations segregate with proximal symphalangism and multiple synostosis syndrome, both of which are skeletal dysplasias resulting from decreased noggin activity." (PMID 31323019, 2019).
NOG also shares sentences with these, for which no sentence is quoted: Alzheimer disease (2 papers); Anxiety (2); injury (2); ischemic stroke (2); oligodendroglioma (2); sarcoidosis (2); amyotrophic lateral sclerosis (1); arteriopathy (1); Atrophy (1); atypical hemolytic-uremic syndrome (1); brain hemorrhage (1); bronchopulmonary dysplasia (1); Chiari malformation type II (1); cholangiocarcinoma (1); corneal disease (1); corneal ulcer (1); COVID-19 (1); developmental delay (1); dwarfism (1); esophageal cancer (1); germ cell tumor (1); glioblastoma (1); gynecological neoplasms (1); heart failure (1); hyperopia (1); Hypertension (1); infarction (1); intestinal polyp (1); ischemia (1); kidney cancer (1).
A further 25 diseases each share a sentence with NOG in 1 paper.